GJB2 (gap junction protein beta 2)
Diseases named in the same sentence as GJB2 in open-access papers (continued):
Sharing a sentence is not in itself a finding about the gene and the disease.
hearing loss (continued). "The majority of non-syndromic hearing loss (NSHL) cases are caused by mutations in the GJB2 gene that codes for Cx26 and studies have revealed that mutation type and frequency are largely dependent on ethnicity." (PMID 23967136, 2013). "Mutation in GJB2 gene is the most common factor, mtDNA 12S rRNA also plays an important part in the pathogenesis of hearing loss in Jiangsu Province areas." (PMID 23826813, 2013). "T208P mutation was found in a study that assessed the hearing impairment degree with GJB2 biallelic mutations." (PMID 23967136, 2013). "Mutation in GJB2 gene was the most common factor, mtDNA 12S rRNA also play an important part in the pathogenesis of hearing loss in Jiangsu Province areas." (PMID 23826813, 2013). "GJB2 has been known as the most prevalent responsible gene for deafness worldwide and 14–16% (25–26% for congenital cases) of Japanese hearing loss patients have GJB2 mutations." (PMID 23967202, 2013). "In order to establish the prevalence of GJB2 mutations among deafness patients in this region, we investigated 77 simplex cases of prelingual non-syndromic hearing impairment." (PMID 23503914, 2013). "The DFNB1 subtype of autosomal recessive, nonsyndromic hearing impairment, caused by mutations affecting the GJB2 (connection-26) gene, is highly prevalent in most populations worldwide." (PMID 24039984, 2013). "Unlike Caucasian populations, GJB2 mutations seem to account for a lower percentage of hereditary HL in East Asian populations; however, approximately 43% of the GJB2 hearing loss are caused by c.235delC mutation in Koreans." (PMID 23469187, 2013). "Looking specifically at the genetic causes of hearing loss in our population (n = 138), mutations in the GJB2 gene accounted for 76.1% of the genetic cases." (PMID 23555729, 2013). "Despite the many studies on the involvement of GJB2 mutations in hearing impairment in different populations, there is little information on genetic deafness in Brazil, especially in the Amazon region." (PMID 23503914, 2013). "Among the deafness-associated genes identified thus far, mutations in GJB2 are the most common cause of monogenic hearing impairment worldwide." (PMID 23451214, 2013). "To further extend the epidemiological data of common gene mutations in Chinese population, we screened the GJB2 and mitochondrial 12S rRNA genes to determine the etiology of hearing loss in Jiangsu Province." (PMID 23826813, 2013). "For example, the GJB2 gene accounts for approximately 20-40% of genetic hearing loss in Caucasian populations but only 10% of genetic hearing loss in Korean populations." (PMID 22938506, 2012). "More than 50% of cases of autosomal recessive non-syndromic hearing loss in many world populations are attributed to mutations in GJB2 gene encoding connexin 26 (OMIM: 121011)." (PMID 22567152, 2012). "In typical areas of China, GJB2 gene mutations account for the etiology in about 18.31% of patients with hearing loss, SLC26A4 mutations account for about 13.73%, and the 12S rRNA A1555G mutation accounts for 1.76%." (PMID 22389666, 2012). "In fact, cochlear implantation has resulted in remarkable improvement in auditory skills and development of speech production for patients with profound hearing loss associated with GJB2 mutations." (PMID 22384008, 2012). "The 235delC mutation of GJB2 gene is considered as a risk factor for the non-syndromic hearing loss (NSHL), and a significant difference in the frequency and distribution of the 235delC mutation has been described world widely." (PMID 22747691, 2012). "Nonsyndromic inherited hearing impairment caused by mutations in GJB2, SLC26A4, or mtDNA 12S rRNA typical accounts for 33.8% of the cases of deafness in areas of China." (PMID 22389666, 2012). "GJB2 mutations, as well as other connexins, have been reported as causative for several syndromic forms of hearing loss associated to skin problems." (PMID 22547955, 2011).
hearing loss (continued). "GJB2 mutations are the most common genetic etiology of prelingual non-syndromic sensorineural hearing loss." (PMID 21738759, 2011). "Mutations in the GJB2 gene, which encodes connexin 26, are a frequent cause of congenital non-syndromic sensorineural hearing loss." (PMID 21738759, 2011). "As elsewhere, the most common gene involved in hearing loss in the Middle East is GJB2, which is responsible for 27% of congenital hearing loss among Israeli Jews and 14% of congenital hearing loss among Palestinian Arabs." (PMID 21917145, 2011). "Although mutations of the connexin 26-encoding GJB2 gene are the most common cause of hereditary hearing loss in most world populations, they occur at different frequencies across populations." (PMID 21811586, 2011). "Mutations in the GJB2 gene have also been implicated in modulating the severity of hearing loss associated with the A1555G mutation." (PMID 21119891, 2010). "Mutations in the GJB2 gene are the most common cause of nonsyndromic recessive hearing loss in China." (PMID 21122151, 2010). "Molecular diagnostic testing of individuals with congenital sensorineural hearing loss typically begins with DNA sequencing of the GJB2 gene." (PMID 20668687, 2010). "To explore the role of the GJB2 gene and the A10 S variant in the TRMU gene in the hearing loss phenotype of this pedigree, we screened GJB2 and A10 S variant in maternal individuals." (PMID 20822538, 2010). "The APEX array comprises a panel of 198 sensorineural hearing loss mutations in six nuclear genes (GJB2, GJB6, GJB3, GJA1, SLC26A4 and SLC26A5) and two mitochondrial genes (MTRNR1 and MTTS1)." (PMID 20668687, 2010). "This study focused on clarifying the impact of GJB2 IVS1+1G>A mutation and the promoter region of this gene among Chinese patients with hearing loss, especially those with pathogenic mutation in only one allele of the GJB2 gene coding region." (PMID 21122151, 2010). "By direct sequencing analysis of 7133 Chinese patients with hearing impairment, we found 212 unrelated patients with monoallelic GJB2 coding region mutation." (PMID 21122151, 2010). "The percent of postlingual hearing loss in the 212 nonsyndromic hearing loss patients group with monoallelic mutation in the coding region of GJB2 is 6.6%(14/212) and that of preligual is 93.4% (198/212)." (PMID 21122151, 2010). "Almost 50% of the patients with nonsyndromic hearing loss in these typical Chinese areas carried GJB2 or SLC26A4 mutations." (PMID 19744334, 2009). "Mutations in the GJB2 gene accounted for 18.31% of the patients with nonsyndromic hearing loss, 1555A>G mutation in mitochondrial DNA accounted for 1.76%, and SLC26A4 mutations accounted for 13.73%." (PMID 19744334, 2009). "Ten patients with a family history of hearing loss showed mutations in GJB2, GJB3, GJB6, SLC26A4, mtDNA 12S rRNA, or mtDNA tRNAser(UCN) in our study population." (PMID 19744334, 2009). "The GJB2 gene accounted for the etiology in about 18.31% of the patients with hearing loss, SLC26A4 accounted for about 13.73%, and mtDNA 1555A>G mutation accounted for 1.76%." (PMID 19744334, 2009). "In summary, this study revealed a unique GJB2 mutation spectrum in Chinese patients with nonsyndromic hearing impairment." (PMID 19366456, 2009). "More than 150 mutations, polymorphisms and unclassified variants have been described in GJB2 to account for about 8–40% of molecular etiology of the patients with nonsyndromic hearing impairment." (PMID 19040761, 2008). "Study of GJB2 gene revealed that 30.4% of the patients with hearing loss in Inner Mongolia carried GJB2 mutations." (PMID 19040761, 2008). "Our previous study on the prevalence of GJB2 mutations in Chinese patients with hearing impairment demonstrated that GJB2 mutations were detected in 30.4% of the patients in ChiFeng city." (PMID 19040761, 2008).
hearing loss (continued). "In another study, performed in patients with hearing loss, mutations in the GJB2 gene were found in 33.5% of cases, and only the 35delG mutation was identified in 84.2% of mutant alleles." (PMID 18278224, 2007). "In approximately one third of the cases of hearing impairment due to mutations in the GJB2 gene, an audiometric pattern of progressive hearing loss is found, as opposed to the two thirds of cases with the typical non-progressive pattern." (PMID 18278224, 2007). "Data obtained in the present study confirmed the high prevalence of GJB2 gene 35delG mutation in cases of profound and bilateral non-syndromical sensorineural hearing loss." (PMID 17119768, 2006). "In the present study, 32 children with idiopathic hearing loss underwent GJB2 gene 35delG mutation tracking." (PMID 17119768, 2006). "These milestones provide a translational framework for treating GJB2-related hearing loss." (PMID 41516362, 2026). "This review focuses on mechanism-oriented therapeutic strategies for GJB2-associated hearing loss, investigating how different types of GJB2 variants correspond to distinct clinical phenotypes and underlying pathogenic mechanisms, and aims to determine appropriate treatments." (PMID 42196291, 2026). "Although prenatal diagnosis is not currently recommended for potential homozygous carriers of c.109G>A, studies indicate that when this variant occurs in combination with other GJB2 variants, it may lead to severe early-onset hearing loss." (PMID 40421383, 2025). "In addition, it has been described that non-syndromic hearing loss is more frequently autosomal recessive, where approximately 50% involve the DFNB1 locus, caused by variants in the GJB2 and GJB6 genes." (PMID 41254778, 2025). "We postulate that mutations in GJB2 may contribute to age-dependent accumulation of reactive oxygen species (ROS), thereby potentiating the severity of hearing impairment." (PMID 40943139, 2025). "As GJB2 variants were diverse and some were non-penetrant, and genotypes were associated with the penetrance time of hearing impairment, variants in GJB2 could present as delayed and progressive deafness after birth." (PMID 39757988, 2025). "Here, we report a novel large intragenic deletion within the GJB2 gene in a Mayan family with several members affected by congenital non-syndromic hearing loss." (PMID 40981390, 2025). "The GJB2 gene is frequently mutated in individuals with hearing impairment in the world." (PMID 40943139, 2025). "In this work, we identified a novel 200 kb deletion spanning more than 20 kb each side of the CRYL1 locus and present in heterozygosis in three unrelated hearing loss patients from northwestern Spain who are also heterozygous for the most prevalent pathogenic GJB2 mutation in Europeans (c.35delG)." (PMID 40565562, 2025). "GS of the remaining 15 cases yielded diagnoses in three individuals, including the identification of deletions in LOXHD1 and STRC, and a recently characterized 125 kb deletion overlapping CRYL1, which refines a critical upstream regulatory region associated with GJB2-related hearing loss." (PMID 41367487, 2025). "The dominant-negative mutation R75W in GJB2, which arises de novo during early embryogenesis, underlies syndromic hearing loss as well as deafness with palmoplantar keratoderma and is detected in 0.09% of probands with sensorineural hearing loss in Han Chinese populations." (PMID 40059830, 2025). "Nonetheless, the development of more mutation-specific base-editing cassettes packageable into an all-in-one AAV vector is required to enhance the precision and therapeutic potential of base editing for hearing loss caused by GJB2 mutations and other genetic diseases." (PMID 40059830, 2025). "Additionally, genetic predisposition (e.g., GJB2 variants encoding Cx26) interacts with environmental factors to produce variable phenotypic expressions of hearing loss, underscoring the multifactorial nature of connexin-related pathologies." (PMID 41463117, 2025).
hearing loss (continued). "GJB2 is the first gene identified that is responsible for autosomal recessive non-syndromic hearing loss and accounts for up to 50% of all cases of pre-lingual hearing loss." (PMID 41227304, 2025). "Identifying comparable diagnostic rates with our cohort of GJB2 carriers due to pathogenic variants in other ARHL genes highlights the large locus heterogeneity that drives nonsyndromic hearing loss and the substantial GJB2 carrier frequency in the general population." (PMID 41367487, 2025). "Furthermore, over 30 genes associated with hearing loss are small enough to fit within the scAAV vector, including some of the most prevalent causes of hearing loss worldwide, such as GJB2 and TMPRSS3 (Table EV1)." (PMID 40859056, 2025). "Recessive GJB2 variants, the most common genetic cause of hearing loss, may contribute to progressive NSHL." (PMID 40943139, 2025). "More than 20 years on from the discovery of GJB2, studies such as the Human Genome Project of 2003 and the 100,000 Genomes Project of 2018 have advanced the technology for sequencing and increased our understanding of genes implicated in hearing loss." (PMID 39428589, 2025). "However, the presence of both GJB2 mutations associated with deafness and unrelated mutations highlight the intricate genetic factors contributing to hearing loss." (PMID 40004458, 2025). "Likewise, common etiologies of congenital hearing loss such as mutations to the GJB2 gene which encode the connexin 26 (Cx 26) protein and enlarged vestibular aqueduct (EVA) result in normal or near normal SGN density." (PMID 40183851, 2025). "Our findings suggest that an ABE-based base-editing strategy could be an optimal treatment for the dominant form of GJB2-related hearing loss, GJB2-related skin diseases, and other deafness-related mutations, especially single-base substitutions." (PMID 40059830, 2025). "The GJB2 p.I203T variant, although previously considered a polymorphism, may exert pathogenic effects and be associated with more severe hearing impairment." (PMID 40943139, 2025). "The first two such deletions identified, del(GJB6-D13S1830) (spanning 309 kb) and del(GJB6-D13S1854) (spanning 232 kb), affected the GJB6 locus, immediately telomeric to GJB2, leading to the assumption that GJB6 was also involved in non-syndromic hearing loss in a digenic fashion with GJB2." (PMID 40565562, 2025). "Additionally, other genes such as the CEVA haplotype, FOXI1, KCNJ10, POU3F4, and possibly GJB2 are implicated in 50 %–60 % of cases of hearing loss and enlargement." (PMID 39481243, 2024). "Thus, it is important to conduct genetic testing on HL patients and analyze the frequency distribution and genotype—phenotype correlation of GJB2 mutations in hearing loss patients to support genetic diagnosis and counseling." (PMID 39767564, 2024). "GJB2 protein encoded by GJB2 (Cx26) has about 220 mutation SNPs associated with hearing loss." (PMID 38212800, 2024). "Besides GJB2-related hearing loss, we also identified 3.3% (1 in 31) of women carrying the USH2A gene that caused Usher syndrome, characterized by moderate to severe deafness at birth and progressive retinitis pigmentation." (PMID 38553482, 2024). "Two GJB2 gene mutations, rs72474224 and rs2274084, were associated with nonsyndromic hearing loss." (PMID 38890579, 2024). "Furthermore, two of three individuals with homozygous LoF variants in GJB2, a gene associated with nonsyndromic sensorineural hearing loss, were confirmed to have hearing loss." (PMID 38630824, 2024).
hearing loss (continued). "Despite the high prevalence of the GJB2 c.35del variant and the fact that hearing loss is the most prevalent sensorineural disorder in humans and a major health concern worldwide, the pathogenetic pathway from GJB2 loss of function to hearing loss is still unclear." (PMID 38626573, 2024). "However, the GJB2 gene exhibits a high number (approximately 135) of pathogenic variants associated with hearing loss." (PMID 38790217, 2024). "Although the CLDN14 gene is relatively small, it consists of a single coding exon, has a coding region of 720 nucleotides, and is associated with a limited number of mutations linked to hearing loss; another gene, GJB2, with a similar structure (one single coding exon) is also involved in deafness." (PMID 38790217, 2024). "This in vitro organoid model may facilitate drug screening and cell therapy for GJB2‐associated hearing loss." (PMID 39188517, 2024). "We concluded that these hearing impairments may be due to destabilization of the protomer structure of GJB2 caused by the R143W variant." (PMID 38730444, 2024). "GJB2 is the most commonly affected gene in non-syndromic hereditary hearing loss in many regions of the world, particularly in Europe, the Middle East, North Africa, and the countries affected by colonization, such as the Americas, and is known to result in congenital bilateral profound SNHL." (PMID 39062005, 2024). "This process was once considered the main pathological mechanism of GJB2-related hearing loss." (PMID 37333892, 2023). "However, individual case analyses revealed that in three cases with four ears, hearing loss progressed by 10 dB or more until the last observation, suggesting the presence of progressive sensorineural hearing loss caused by GJB2 gene mutations." (PMID 38069086, 2023). "Although not directly involved in mechanotransduction or signal transmission from hair cells to spiral ganglion neurons (SGNs), mutations in Gjb2 are the most prevalent cause of congenital non-syndromic hearing loss, accounting for >25% of all genetic hearing loss worldwide." (PMID 37368868, 2023). "In 26 patients with the GJB2 variants in a homozygous or compound heterozygous state, hearing loss is characterized as early (detected up to 3 years) (92.3%), symmetric (88.5%), sensorineural (100.0%) and variable in severity (moderate—11.6%, severe—26.9%, and profound—61.5%)." (PMID 37239361, 2023). "However, together with GJB2 and GJB6 (which are outside of the microdeletion interval), CRYL1 constitutes part of the DFNB1 locus, which accounts for nearly half of the sensorineural hearing loss in certain populations." (PMID 37239394, 2023). "The contribution of the GJB2 gene variants to the etiology of hearing impairment (HI) in the total sample of patients was 15.8% (26 out of 165) and significantly differed in patients of different ethnicity (5.1% in Buryat patients and 28.9% in Russian patients)." (PMID 37239361, 2023). "Second, our findings point to multiple genes that have been reported to cause Mendelian forms of hearing loss previously, including EYA4, CDH23, TRIOBP, and GJB2, the latter being the most commonly reported gene in autosomal-recessive non-syndromic hearing loss." (PMID 35580588, 2022). "Indeed, in a previous study, we found accelerated ARHL in an animal model of Gjb2 deletion, the gene of the GJ protein Cx26, whose mutations are a major cause for congenital nonsyndromic profound hearing loss." (PMID 36016655, 2022). "The GJB2 c.-23 + 1G>A variant accounts for 0.2%–1.89% of hearing loss patients in China." (PMID 36568381, 2022). "However, because of the higher frequency of GJB2-related hearing loss in the Russian Federation, the overall prevalence of mutations in the GJB2 gene and the 33 studied genes among the NSHL Russian patients was higher (55%) than in these cohorts." (PMID 36555390, 2022). "In this study, the most common gene in ECS was GJB2 associated with GJB2-related hearing loss." (PMID 36072675, 2022).